BMAL1 (basic helix-loop-helix ARNT like 1)
Diseases named in the same sentence as BMAL1 in open-access papers (continued):
Sharing a sentence is not in itself a finding about the gene and the disease.
cancer (continued). "Fourth, maintenance of levels of BMAL1 in cancer cells requires functional mTORC1 and mTORC2 complexes." (PMID 27285754, 2016). "Compared with those in normal epithelium, the mRNA levels of PFKFB3 were increased in both cancer tissues and its surrounding tissues, which were accompanied with significant decreases in the mRNA levels of BMAL1 and CLOCK in the same tissues." (PMID 27079271, 2016). "Our findings indicate BMAL1 as a readout of compromised PTEN and PER2 function and suggest that BMAL1 is involved in the progression of cancer." (PMID 27285754, 2016). "In our research, mRNA expression of NPAS2 was robustly decreased after PER1 knockdown, indicating that the compensatory effect on CLOCK/BMAL1 was weakened due to PER1 knockdown in cancer cells." (PMID 27602964, 2016). "Specifically, BMAL1 has been shown to suppress cancer cell invasion by antagonizing the oncogene B-cell lymphoma w (Bcl-w), thus suppressing matrix metalloproteinase-2 (MMP-2) accumulation and blocking the PI3K-AKT-MMP2 signaling pathway." (PMID 26220712, 2015). "Heterozygous Bmal1-knockout mice exhibit increased cancer-proneness, spontaneous as well as after genotoxic challenge (ionizing radiation)." (PMID 26019524, 2014). "We demonstrated that knockdown of Bmal1 by RNA interference promoted cancer cell invasion, whereas its overexpression reduced cellular invasiveness." (PMID 23563360, 2013). "Bmal1 knockdown-induced cancer cell invasion was accompanied by activation of the PI3K-Akt-MMP-2 pathway, and was prevented by inhibitors of PI3K, Akt or MMP-2." (PMID 23563360, 2013). "In conclusion, we showed that Bmal1 attenuates cancer cell invasion by suppressing the PI3K-Akt-MMP-2 pathway." (PMID 23563360, 2013). "Future research must concentrate on developing drugs that can accurately regulate the nuclear-cytoplasmic distribution of p62, which may alter the protein levels of BMAL1 in cells and be applied in cancer therapy." (PMID 40638681, 2025). "Our preliminary findings also suggested that remodeling the accumulation capacity of p62 in the nucleus may represent a potential strategy for targeting BMAL1 in cancer therapy." (PMID 40638681, 2025). "Finally, knocking down BMAL1 can enhance the efficacy of certain first-line cancer therapeutic drugs, including venetoclax, dasatinib, and sorafenib." (PMID 38703241, 2024). "This hypothesis is supported by the promotion of cancer cell invasion in Bmal1-depleted cells and its reduction when Bmal1 was overexpressed in a similar study." (PMID 38257148, 2024). "Additionally, it has been demonstrated that the core BMAL1::CLOCK transcription apparatus is crucial for maintaining stemness in at least two distinct cancer types." (PMID 38892035, 2024). "Therefore, melatonin is the one that enhances PER2 and CLOCK and decreases BMAL1 in this type of carcinoma." (PMID 38892035, 2024). "Here, we briefly discuss the roles of CLOCK/BMAL1 in in several representative cancers." (PMID 36647780, 2023). "Thus, genetic disruption BMAL1 would produce a polarized effect on cancer cells and host stromal cells such as CAFs as described in our study." (PMID 37330661, 2023). "Here, our results provide molecular insights into this HCC-clock crosstalk by unveiling that the core clock transcription factor BMAL1::CLOCK is hijacked by cancer cells to fuel rapid cell proliferation and inhibit apoptosis in HCC, independent of the genetic background or core clock oscillations." (PMID 36595671, 2023). "Importantly, clinical studies indicate that high expression of BMAL1 correlates with poor prognosis for cancer patients." (PMID 36725890, 2023). "Using this model, we effectively investigated the role of BMAL1 in cancer cell lines." (PMID 36806631, 2023).
cancer (continued). "High expression of BMAL1 in cancer cells could decrease sensitivity/increase resistance to oncotherapeutic agents and result in poor cancer treatment outcomes." (PMID 36725890, 2023). "Therefore, our results are consistent with findings from the literature, evidencing a potential role for Bmal1 and the circadian clock in cancer cells’ sensitization to PTX and further enhanced apoptosis at specific time points." (PMID 37504857, 2023). "Thus, BMAL1 serves as a core component of the master transcriptional machineries to control cancer cell motility and metastasis." (PMID 37330661, 2023). "Therefore, additional studies are warranted to explore the basic role of BMAL1 in cancer and its mechanism of action in the development and treatment of cancer." (PMID 36725890, 2023). "Bmal1 suppresses cancer cell invasion by blocking the PI3K‐AKT‐MMP‐2 signaling pathway." (PMID 36066207, 2022). "Interestingly, cancer stem cells display robust circadian rhythm with exquisite dependency on core clock transcription factors, BMAL1 and CLOCK, for optimal cell growth." (PMID 35984550, 2022). "Interestingly, in embryonic fibroblasts isolated from Bmal1−/− mice, an elevated glycolysis level and increased lactate production was observed, similar to the metabolic phenotype observed in cancer cells." (PMID 34948470, 2021). "Thus, BMAL1-KD alters the dynamics of F-actin/G-actin turnover and induced an increased cortical distribution of F-actin, which finally reduced cancer cell migration, and invasion." (PMID 34065633, 2021). "BMAL1 is a unique core clock regulator and defects in BMAL1 leads to circadian disruption and various abnormalities, such as defects in glucose–lipid metabolism early aging, skeletal mandibular hypoplasia, and cancer." (PMID 34741025, 2021). "Analysis of multiple human cancer (TCGA) samples revealed that an index of higher core circadian clock gene (BMAL1, PER1/2/3, CRY1/2, CLOCK) expression is related to downregulated MMR pathways, possibly indicating the occurrence of fewer mismatch events, though this was not directly assessed." (PMID 33794967, 2021). "Therefore, the relationship between BMAL1 and cancer development is complex and requires deeper investigation to reveal molecular mechanistic insights." (PMID 32388500, 2020). "Thus our data support the links between BMAL1 and mTOR pathway, which suggests BMAL1 regulation of protein synthesis and the role of circadian timing in cancer development." (PMID 32388500, 2020). "Altogether, these results indicated that BMAL1 may promote or inhibit oncogenesis depending on the types of cancer." (PMID 32231148, 2020). "Bmal1 and Npas2 could regulate cancer cell proliferation and invasion through suppressing the transcription of c-Myc." (PMID 32437452, 2020). "The results above may result from the differential expression of BMAL1 in various cancer cell lines, so that BMAL1 may regulate the occurrence and development of cancers through different signaling pathways." (PMID 31346317, 2019). "Recent studies have indicated that the hypoxic response in cancer could be directly controlled by the circadian rhythm Clock/Bmal1." (PMID 31311204, 2019). "In addition to controlling the function of biological rhythms, BMAL1 also plays important roles in aging, cardiovascular disease, immune diseases and cancer." (PMID 31346317, 2019). "Metastatic cancers present high levels of Clock or Bmal1 genes." (PMID 31311204, 2019). "Furthermore, it has also been established that downregulated PER3, CRY2 and BMAL1 was attributed to the more advanced stages of cancer." (PMID 31151182, 2019). "Because prior studies have revealed that MYC can repress BMAL1 expression in specific cancer cells, we co-transfected the cells with siMyc or scrambled oligonucleotides to determine the extent to which HNF4α repression of Bmal1could be indirect through changes in Myc expression." (PMID 30341289, 2018).
cancer (continued). "Ectopic expression of BMAL1 in HepG2 cells resulted in a transient loss of HNF4α expression; and cancer cells, but not AML12 cells overexpressing BMAL1, showed reduced proliferative capacity over 48 h." (PMID 30341289, 2018). "Importantly, 4T1 cancer cells disrupt expression patterns of Bmal1, Cry1, and Clock in the liver, a possible upstream of the decreased OXPHOS expression." (PMID 28388556, 2017). "In addition, the expression of key clock genes whose products generate feedback inhibitory effects on BMAL1/CLOCK transcription activity in cancer tissues and its surrounding tissues was distinct from that in normal tissues." (PMID 27079271, 2016). "In addition, BMAL1 has also been reported to be involved in cell proliferation and cancer cell invasion through regulating different signaling pathways." (PMID 26753996, 2016). "The aim of the present study was to investigated whether Bmal1 influences the invasiveness of cancer cells." (PMID 23563360, 2013). "In the present study, we demonstrated that Bmal1 suppresses cancer cell invasion." (PMID 23563360, 2013). "Finally, enrichment of Kyoto Encyclopedia of Genes and Genomes (KEGG) pathways found cancer pathways as highly enriched in BMAL1 targets (DAVID, p<0.001), notably in components of the cell cycle and in transforming growth factor beta (TGFβ) signaling." (PMID 21364973, 2011). "Notably BMAL1 regulates the involvement of Nrf2 in carcinogenesis, for example, its deletion downregulates the Nrf2-mediated antioxidant pathway and significantly increases the amount of IL-1β, which promotes cancer." (PMID 39139571, 2024). "Although genetic deletion of BMAL1 causes circadian rhythmic disruption, we cannot exclude non‐clock functions of Bmal1 in participating in cancer metastasis because genetic deletion of the core clock gene would have broad impacts on alterations of gene expression profiling in cancer hosts." (PMID 37330661, 2023). "Since BMAL1 was shown to regulate several critical cellular processes such as cell cycle progression, lipid, and glucose metabolism, redox state, and stress response, this highlights the putative crosstalk between the molecular clock and cancer development and progression." (PMID 34361055, 2021). "Furthermore, patients with thyroid cancer expressed higher levels of Clock, Bmal1, and Per2 and reduced levels of Cry2 compared to age-matched cancer-free controls, which correlated to the extent of sleep disruption measured by the Pittsburgh sleep quality index in these patients." (PMID 34958429, 2021). "Metabolic dysregulation in cancers may result in disruption of Bmal1 in a hypoxic-dependent way." (PMID 31311204, 2019). "Metabolic dysregulation in cancers may results of disruption of Bmal1 in a hypoxic-dependent way." (PMID 31331376, 2019). "Clockophagy, the selective autophagic degradation of BMAL1 by p62 in response to the ferroptosis inducer RSL3, is critical for ferroptosis in ferroptosis-sensitive cancer cell lines." (PMID 40877242, 2025). "The E-box regulators BMAL1, CLOCK, CRY1, and PER1, as proteins, play a role in several cancers, and MB should be added to the list of those cancers." (PMID 40002179, 2025). "The molecular clock’s main components, including BMAL1, CLOCK, and REV-ERBα, regulate immune cell formation, activity, and trafficking, altering cancer immune surveillance." (PMID 38892035, 2024). "It normalizes the expression of circadian proteins like BMAL1 and CLOCK, which are often disrupted in liver cancer cells, aiding in the treatment of cancer." (PMID 39062777, 2024). "Circadian rhythms are controlled by a set of regulatory molecules like the protein CLOCK (circadian locomotor output cycles kaput), brain and muscle ARNT-like protein 1 (Bmal1), PER1 and PER2, all of which seems to be dysregulated in cancer." (PMID 39199335, 2024).
cancer (continued). "Specifically, BMAL1 expression elevated cancer cell secreting RAB27A which induced the migration of endothelial cells and cancer cells." (PMID 38607733, 2024). "A series of experiments were conducted to demonstrate the mechanisms of BMAL1 regulating EMT and cancer proliferation in vitro and in vivo." (PMID 36806631, 2023). "The CLOCK gene enhances VEGF-mediated angiogenesis in cancer cells and metastatic invasion by interacting with HIF-1α/BMAL1." (PMID 36672355, 2023). "Nonetheless, BMAL1, CLOCK, and other core clock genes have been shown to be widely dysregulated at the transcriptional level across cancer types." (PMID 37601651, 2023). "In contrast, KLF9 does not oscillate in entrained MDA-MB-231 cells and circadian expression of BMAL1 and PER1 was slightly irregular in the cancer cell line as well." (PMID 36823570, 2023). "In the cancer cell‐CAF‐co‐implantation model, isolated CAFs from the Bmal1−/− mouse background exhibited a myofibroblast phenotype that boosted cancer metastasis." (PMID 37330661, 2023). "Discovering BMAL1 and CLOCK, the forementioned master transcription factors of circadian rhythms, are required for cancer cell proliferation has encouraged experimental and clinical investigations to inform novel anticancer strategies." (PMID 36937362, 2023). "Recently it has been reported that curcumin targets different molecules regulating the circadian timing system with anti-cancer activity such as PER2, BMAL1, and CLOCK." (PMID 36796229, 2023). "Two groups have shown that MYC (both MYC and MYCN) can inhibit BMAL1 and CLOCK function in cancer cells and disrupt the circadian dynamics of the core clock molecules." (PMID 37601651, 2023). "CLOCK genes such as BMAL1 and REV-ERB mainly play an anticancer role while DEC has both anticancer and cancer-promoting effects in relevant literature." (PMID 38189049, 2023). "More lately, our lab and others have shown that the master circadian E-box-binding regulators, BMAL1 and CLOCK, also have important functions in several cancer types." (PMID 37601651, 2023). "For example, the BMAL1-CLOCK/NPAS2 heterodimer has been reported to repress c-Myc, an oncogene that contributes to the genesis of many human cancers, and whose protein expression is closely correlated with cell proliferation rates." (PMID 36768253, 2023). "GEPIA was used to understand the messenger (m)RNA expressions of circadian rhythm-related factors in the PER family (PER1, PER2, and PER3), CRY family (CRY1 and CRY2), BMAL1, and CLOCK in different types of cancer." (PMID 36385012, 2022). "The UALCAN database showed expressions of circadian factors, including PER and CRY family members, BMAL1 (ARNTL), and CLOCK, with differential expression levels between different types of cancers and normal tissues." (PMID 36385012, 2022). "As EMT promotes invasiveness of cancer cells, a scratch-wound healing assay and an in vitro Matrigel invasion assay were performed to check if the leaned epithelial–mesenchymal balance induced by BMAL1-KD could affect the migration and invasion properties of CRC cells." (PMID 34065633, 2021). "Additional potential targets for treating cancer include several ROR isoforms and positive transcriptional regulators of Bmal1 expression." (PMID 34615982, 2021). "Unsupervised principal component analysis with the main cancer invasiveness-enriched genes (ASPN, GLT8D2, OLFML2B, CRISPLD2, ADAM12, POSTN, and PRRX1) allowed for the discrimination of subgroups of BMAL1-dependent CRC patients (p = 9.9 × 10−4)." (PMID 34065633, 2021). "This regulation suggests a relationship between Cry1/2 and Bmal1 and Prkaa2, Ccnd1and Nf1 in promoting CJL mediated cancer." (PMID 31523185, 2019).
cancer (continued). "In numerous cancers, the dysfunction of the canonical WNT pathway is accompanied by alterations of the circadian genes (CLOCK, BMAL1, PER)." (PMID 31803621, 2019). "The link identified in our research between BMAL1, CLOCK, and Rho GTPase activity presents an innovative therapeutic targeting strategy of Rho GTPase in cancer." (PMID 30287810, 2018). "Numerous studies reported that individual molecular components of the circadian clock, such as BMAL1, PER2, or PER1 suppress proliferation or increase the sensitivity to anti-cancer drugs in different cancer cell lines." (PMID 28425940, 2017). "In an in vitro cancer model, disrupting the negative limb of the transcription translation feedback loop is associated with enhanced cell death Therefore, it might be expected that disruption Bmal1 (i.e., the positive limb) could lead to lower cell death." (PMID 24941219, 2014). "The circadian clock, governed by core-clock genes such as BMAL1 and PER2, orchestrates various physiological processes, including metabolism, cell proliferation, and responses to medications, making them a crucial target for improving cancer therapy outcomes." (PMID 40382284, 2025). "While many cancer cell types continue to exhibit oscillations of the circadian clock, it was shown that deregulation of the key clock genes PER1, PER2, PER3, CRY1, CRY2, BMAL1, and CLOCK occurs in certain human malignancies." (PMID 38892035, 2024). "Core genes such as BMAL1 and CLOCK are positive transcription factors in circadian rhythms, which are involved in the regulation of immune cell function, and their overexpression promotes cancer cell proliferation and invasion." (PMID 39139571, 2024). "Therefore, by influencing the functions of CLOCK and BMAL1, CLK8 elicits improvements in aging, emotional disorders, and the effectiveness of cancer treatment." (PMID 36647780, 2023). "The PER1, PER2, and PER3 genes regulate cell growth, proliferation, and apoptosis, CRY1 and CRY2 regulate the transcription G1/S and G2/M cell cycle checkpoints, while BMAL1 and NPAS2 inhibit the proliferation and invasion of cancer cells by suppressing the c-Myc transcription factor." (PMID 36672355, 2023). "Interestingly, down-regulation of PER1-3, CRY2, NPAS2, BMAL1, as well as CLOCK gene expression, correlates with high histological grade and poor prognosis and short survival in different cancers." (PMID 36672355, 2023). "Recent studies have discovered pivotal roles for BMAL1 and CLOCK in multiple types of cancers." (PMID 37601651, 2023). "Given the extensive part of the four clock proteins (CRY, PER, BMAL1, and CLOCK), the circadian clock may regulate many cancer mechanisms such as apoptosis and therapeutic resistance." (PMID 35356228, 2022). "Because of the low expression of BMAL1 and CLOCK in the results found, it is possible that this deregulated mechanism aids in the continuous cell proliferation of leukemic cells, as it has been shown in other types of cancer." (PMID 35897788, 2022). "At the same time, we found that BMAL1 expression is higher in invasive cancer cells than in non-invasive cancer cells." (PMID 31346317, 2019). "Therefore, we knocked out the BMAL1 gene in a nearly normal cell line (MCF10A) and an invasive cell line (MDA-MB-231) to study two cancer-related pathways, apoptosis and invasion." (PMID 30375470, 2018). "While BMAL1 and HNF4α are co-expressed in healthy hepatocytes and nontransformed hepatocyte-derived cell lines, we found that cancer cells expressing P1/P2-HNF4α express little to no BMAL1." (PMID 30341289, 2018). "Consequently, CLOCK and BMAL1 control the expression of the components of the RHOA-ROCK-CFL pathway, which alters the dynamics of F-actin/G-actin turnover and promotes cancer cell proliferation, migration, and invasion." (PMID 30287810, 2018). "Notably, the effects of BMAL1 and CLOCK overexpression in this assay were both mild, potentially due to the intrinsically high endogenous expression of BMAL1 and CLOCK in cancer cells." (PMID 30287810, 2018).